TRBV7-3 (T cell receptor beta variable 7-3)
Description:
Probable non-functional open reading frame (ORF) of V region of the variable domain of T cell receptor (TR) beta chain. Non-functional ORF generally cannot participate in the synthesis of a productive T cell receptor (TR) chain due to altered V-(D)-J or switch recombination and/or splicing site (at mRNA level) and/or conserved amino acid change (protein level). Alpha-beta T cell receptors are antigen specific receptors which are essential to the immune response and are present on the cell surface of T lymphocytes. Recognize peptide-major histocompatibility (MH) (pMH) complexes that are displayed by antigen presenting cells (APC), a prerequisite for efficient T cell adaptive immunity against pathogens. Binding of alpha-beta TR to pMH complex initiates TR-CD3 clustering on the cell surface and intracellular activation of LCK that phosphorylates the ITAM motifs of CD3G, CD3D, CD3E and CD247 enabling the recruitment of ZAP70. In turn ZAP70 phosphorylates LAT, which recruits numerous signaling molecules to form the LAT signalosome. The LAT signalosome propagates signal branching to three major signaling pathways, the calcium, the mitogen-activated protein kinase (MAPK) kinase and the nuclear factor NF-kappa-B (NF-kB) pathways, leading to the mobilization of transcription factors that are critical for gene expression and essential for T cell growth and differentiation. The T cell repertoire is generated in the thymus, by V-(D)-J rearrangement. This repertoire is then shaped by intrathymic selection events to generate a peripheral T cell pool of self-MH restricted, non-autoaggressive T cells. Post-thymic interaction of alpha-beta TR with the pMH complexes shapes TR structural and functional avidity.
Synonyms: TRBV73; TCRBV6S1A1N1; TCRBV7S3
Gene: T-cell receptor variable (V) gene on chromosome 7 (142,384,329 to 142,384,841, forward strand). Ensembl gene ENSG00000211714.
Subcellular location: Cell membrane
Gene Ontology:
Biological process: cell surface receptor signaling pathway
Cellular component: plasma membrane
Homologues: Orthologues: macaque TRBV7-3 (54% identical). Paralogues in human: TRBV7-2 (83% identical), TRBV7-1 (77% identical), TRBV7-6 (71% identical), TRBV7-4 (70% identical), TRBV7-7 (70% identical), TRBV7-9 (68% identical), TRBV11-1 (64% identical), TRBV11-2 (64% identical), TRBV11-3 (61% identical), TRBV12-4 (57% identical), TRBV17 (56% identical), TRBV12-3 (55% identical), and 39 more.